BRAF (B-Raf proto-oncogene, serine/threonine kinase)
Diseases named in the same sentence as BRAF in open-access papers (continued):
Sharing a sentence is not in itself a finding about the gene and the disease.
melanoma (continued). "There is also recent evidence from our group demonstrating that some melanomas with BRAF V600E mutations may be intrinsically resistant to inhibitors of BRAF as a result of cyclin D1 amplification." (PMID 19156138, 2009). "Interestingly, BRAF mutations are mutually exclusive with NRAS mutations in melanoma and KRAS mutations in colorectal cancer." (PMID 19492075, 2009). "The discovery of activating oncogenic mutations in BRAF in over 60% of melanomas has raised expectations that melanoma may be amenable to targeted therapy." (PMID 19156138, 2009). "Given that BRAF is more commonly mutated in melanomas, we hypothesized that targeting the BRAF effector arm alone would be sufficient to affect cell proliferation and in vivo tumor growth." (PMID 19492075, 2009). "This is contrary to our initial hypothesis about BRAF playing a dominant role in tumor cell signaling in melanomas bearing an NRAS mutation." (PMID 19492075, 2009). "Furthermore, the MITF gene is amplified in 10-15% of melanomas carrying a mutated BRAF, supporting the view that continued expression of MITF is essential in melanoma cells." (PMID 19828018, 2009). "However, BRAF mutations are thought to develop early in the pathogenesis of melanomas, and analyses of a series of paired primary and metastatic lesions from the same patients indicate that BRAF mutations are preserved in metastases." (PMID 19861964, 2009). "We found that mutually exclusive mutations of NRAS and BRAF genes occur at quite same rate in cultured and uncultured melanomas (either primary or metastatic lesions), confirming that they represent an early event within the cascade of alterations involved into the melanomagenesis." (PMID 19799798, 2009). "Activating BRAF mutations are present in approximately 50% of melanomas." (PMID 18631381, 2008). "Notably, a recent study with melanoma cells has shown for the first time that BRAF mutation increases HIF-1α expression." (PMID 18983642, 2008). "Importantly, we show that BRN2 and MITF expression are strongly correlated with the presence of BRAF mutations in human melanoma samples." (PMID 18628967, 2008). "Furthermore, depletion of endogenous BRN2 reduced the levels of endogenous MITF protein in all melanoma cell lines in which BRAF is mutated." (PMID 18628967, 2008). "In addition, low frequency of BRAF mutations in radial growth phase melanomas, i.e. the early phase of melanoma progression, suggests a correlation with progression rather than initiation." (PMID 18631381, 2008). "In 3 out of 27 (11%) mucosal melanomas (located in head/neck area, pleura and conjunctiva, respectively) the BRAF V600E mutation could be detected." (PMID 19018266, 2008). "Similarly, using standard cDNA microarray chips, gene expression signatures were reported for malignant melanoma cell lines harboring mutations in the BRAF gene when compared to wild type cell lines." (PMID 18631381, 2008). "The panel of seven melanoma cell lines were sequenced for BRAF, N-Ras and c-Kit mutations." (PMID 17245336, 2007). "This increased ERK activity may be the consequence of activating BRAF mutations, which are present in up to 80% of human melanomas." (PMID 16880785, 2006). "This provides an attractive possible mechanism by which the p16/RB pathway could suppress melanoma following mitogenic mutations like BRAF activation." (PMID 16880792, 2006). "An analysis focussing on melanoma patients was performed in the light of evidence supporting a role for increased signalling through RAF/MEK/ERK in the onset and progression of melanoma, and the prevalence of oncogenic V600E BRAF mutations in melanoma biopsies." (PMID 16880785, 2006).
melanoma (continued). "Future prospective studies should include analysis of whether BRAF mutations in melanoma tumors correlate with an increased tendency to metastasize to liver or to multiple organs." (PMID 15613230, 2004). "Mutations of the BRAF gene are the most common genetic alteration in melanoma." (PMID 15361259, 2004). "The data are quite contrast to those of malignant melanomas, where approximately 90% of BRAF mutations involved V599, raising the possibility that the contribution of BRAF mutations in the development of NHL might be different from that of malignant melanoma." (PMID 14612909, 2003). "Therefore, in all, we had a total of 33% of melanoma patients with a BRAF mutation." (PMID 40869231, 2025). "Notably, the BRAF gene represents one of these oncogenic mutations observed in melanoma." (PMID 40818129, 2025). "Interestingly, the potential efficacy of ICIs in Asian patients with BRAF V600-mutant melanoma may be limited by lower TMB, which is associated with reduced UV exposure and Fitzpatrick skin types III–IV, commonly observed in the Japanese population." (PMID 40361336, 2025). "However, the effect of BRAF/MEK-targeted therapy on GM in BRAF-mutated melanoma remains unexplored." (PMID 40659866, 2025). "Interestingly, a study suggested that reduced mitochondrial biogenesis may contribute to intrinsic resistance to MAPKi in a subgroup of melanoma cells with BRAF mutation." (PMID 41284701, 2025). "However, the relationship between ACKR2 expression and BRAF/NRAS mutations in melanoma remains unclear and warrants further investigation." (PMID 40248897, 2025). "In addition, the obtained data suggest that the key molecules RAC1, RAS, and BRAF, which are frequently mutated in human melanoma, may also contain activating mutations in ghM, whilst PTEN may harbor loss-of-function mutations." (PMID 40724880, 2025). "However, these benign lesions already carry the BRAF (v-Raf murine sarcoma viral oncogene homologue B1) exon 15/V600 mutation, which is also characteristic of melanoma, and a high number of nevi on the skin is associated with a higher risk of melanoma." (PMID 40361349, 2025). "Furthermore, in our cohort, 14 of the 200 (7%) melanoma samples had other BRAF mutations, including BRAF V600K (n = 13, 26%) and BRAF V600R (n = 1), and 19 (9.5%) had other miscellaneous BRAF mutations, such as BRAF D594N." (PMID 40869231, 2025). "Moreover, the incidence of BRAF mutations is higher in BMs than in primary melanomas or metastases to other organs, suggesting there may be an independent evolution of subclones." (PMID 40076927, 2025). "Additionally, TOO identification can inform potential clinically relevant resistance mechanisms; for example, melanoma patients with a BRAF V600E mutation are known to benefit from combination BRAF and MEK inhibitors, whilst colorectal patients with the same alteration don’t derive similar benefit." (PMID 40615718, 2025). "Targeted therapies have been developed for BRAF‐mutated melanoma, notably vemurafenib, which showed significant improvement in response rates and overall survival compared to traditional chemotherapy and became the first targeted standard of care for BRAF mutated melanoma." (PMID 41199020, 2025). "Indeed, recent studies have identified sporadic mutations in IDH genes in melanoma, suggesting they may confer a growth advantage, mainly in BRAF-mutant tumors." (PMID 40721981, 2025). "Moreover, for different cancer types this filter needs to be adapted accordingly, e.g. hotspot mutations would be missed by this such as BRAF V600E, found in 35% melanoma patients, and specific genes were recurrently mutated in 20% DLBCL patients, requiring a higher threshold." (PMID 39955561, 2025).
melanoma (continued). "Interestingly, epidemiological studies show melanoma BRAF mutation frequency varies markedly between geographical regions that have similar levels of UV exposure, which is striking for a malignancy largely driven by UV-mediated DNA damage, suggesting a role for other environmental factors." (PMID 41194666, 2025). "Therefore, the underlying pathogenic process in melanoma may be directly connected to the effects of key mutations (BRAF and NRAS) on the endosomal–lysosomal system, an idea that until now has been underappreciated." (PMID 41155412, 2025). "A recent study has suggested that increased Rac1 activity may be one consequence of disruptions of the PTEN tumor suppressor pathway in melanoma, raising the possibility that PTEN-deficient melanomas may represent another potential context for beneficial co-targeting of BRAF/MEK and FAK." (PMID 41109929, 2025). "In 2021, it was proposed that cyclin-dependent kinase 4 and 6 (CDK4/6) inhibitors could be utilized with success for breast cancer, in response to metabolic reprogramming observed in melanoma following standard BRAF/MEK inhibition implicated in both therapeutic response and resistance." (PMID 40872623, 2025). "However, evaluating the oncogene BRAF mutation in codon V600 is still the only companion diagnostic genomic test commonly implemented in clinics for molecularly targeted treatment of advanced melanoma." (PMID 39340537, 2024). "Therefore, future studies could benefit from replacing the currently used melanoma cell line, Mel-Ho, which exhibits a BRAF mutation, with one possessing an NRAS mutation, such as Mel Juso." (PMID 39062529, 2024). "One potential reason for the low presence of immune cells and other microenvironmental components among the melanoma phenotype-associated cells could be the inherent genetic mutations, such as the BRAF mutation, in melanoma cells that drive their low immune cell infiltration and independent growth." (PMID 39350337, 2024). "In conclusion, the inexpensive and frequently prescribed statin–dipyridamole combination therapy may lead to new developments in the treatment of melanoma and may potentiate the effects of vemurafenib for the targeted therapy of BRAF V600E-mutation bearing melanoma patients." (PMID 38540310, 2024). "Therefore, we provided evidence that CTHRC1 is associated with the BRAF(V600E) mutation and could be used as a diagnostic and prognostic biomarker in human colon cancer, thyroid cancer, and melanoma." (PMID 39052013, 2024). "Results showed molecular differences between the two BRAF/NRAS mutated melanoma could be used to classify samples with an accuracy of 87%-89% and 76%-79% based on the classification models applied (i.e., linear discriminant analysis and support vector machine)." (PMID 38820337, 2024). "While vemurafenib, dabrafenib, and encorafenib all belong to the class of BRAF inhibitors used to treat BRAF-mutated melanoma, the selection among them may hinge on various factors, including the patient’s specific mutation, treatment history, and individual tolerance to side effects." (PMID 39582535, 2024). "Moreover, the SP‐01 tumor presents an activating mutation in the ERBB4 gene, which is described as a driver of BRAF wild‐type (WT) melanomas, and SP‐06 presents an oncogenic NRAS mutation, inactivation of NF2, and a truncating mutation in SMARCA4 (in one allele)." (PMID 37798904, 2024). "However, these inhibitors are ineffective in BRAF wild-type melanoma, which lacks BRAF mutations." (PMID 39329914, 2024). "The BRAF mutation increases the risk that melanoma may progress to a terminal stage." (PMID 38467935, 2024). "In some cancers such as advanced melanoma, V600 mutations occur at particularly higher rates in adolescents and young adults when compared to older adults (68% vs. 46%, p < 0.001), identifying age as a potential biomarker for the presence of the BRAF V600E mutation in these tumors." (PMID 38539548, 2024).
melanoma (continued). "Therefore, it has been hypothesized that BRAF mutations in the Celtic population might be reduced as a cause of genetic drift or natural selection to protect this population from melanoma." (PMID 38183457, 2024). "Thus, we conclude that all of the tested BRAF-mutated melanoma cell lines are susceptible to treatment but the response differs and might be predominantly visible in increased apoptosis and/or cell cycle arrest." (PMID 38730718, 2024). "A subsequent German clinical trial on patients with melanoma demonstrated that BRAF/MEK inhibitors could induce much superior therapeutic responses in patients harboring a coexisting BRAF mutation and TERT promoter mutation compared with patients harboring only a BRAF mutation." (PMID 38735658, 2024). "While BRAF mutation is a diagnostic and prognostic biomarker, it may be a predictive biomarker concerning tyrosine kinase inhibitors (TKIs), such as vemurafenib and dabrafenib, for lung cancer and melanoma patients." (PMID 39457498, 2024). "However, the IMspire150 trial showed that a triple combination with atezolizumab significantly prolonged PFS in patients with BRAF-mutated melanoma compared to a combination of vemurafenib (a BRAF inhibitor) and cobimetinib (15.1 months vs. 10.6 months, p = 0.025)." (PMID 39081713, 2024). "A recent study found that BRAF mutations in ctDNA are detectable in more than 75% of melanoma patients harboring BRAF V600E/V600K-positive tumors, suggesting that lacking BRAF mutation-positive ctDNA may be a prognostic indicator for better outcome for metastatic melanoma patients." (PMID 39156972, 2024). "Notably, both MBM-PDO cultures from BRAF wild-type melanomas also had TERT promoter mutations." (PMID 39204387, 2024). "However, the BRAF-mutated melanomas in our cohort trended toward being thicker." (PMID 38183457, 2024). "Ultimately, as indicated by the modest decrease in MMP2 expression levels in the BRAF-mutated cell lines, this finding may contribute to elucidating the previously reported reduction in cell mobility and colony formation within the same melanoma cell lines." (PMID 38338893, 2024). "In addition to S100, the liquid biopsy approach is gaining interest in determining prognosis and predicting treatment, specifically in patients with malignant melanoma through the detection of BRAF mutations in circulating tumor DNA (ctDNA) or the evaluation of circulating tumor cells (CTC)." (PMID 39387479, 2024). "Notably, patients with BRAF mutations tend to be younger than those with other melanoma subtypes." (PMID 38474231, 2024). "Furthermore, PLA1A is a potential diagnostic marker for advanced and BRAF mutant melanoma." (PMID 38357546, 2024). "Notably, the expression of STRA6 was positively correlated with BRAF mutation in TC and melanoma." (PMID 36843593, 2023). "At a multi-day conference, a panel of Latin American experts in oncology and dermatology were provided with questions to address the barriers limiting access to testing for BRAF mutation in patients with melanoma in LA, who may be eligible for targeted therapy to improve their prognosis." (PMID 36998456, 2023). "Therefore, it is possible to hypothesize that inhibitors of glutathione biosynthesis and/or pyruvate dehydrogenase activity could be used in combination with PLX4032 to overcome drug resistance of BRAF-mutated melanoma patients." (PMID 37534247, 2023). "However, PTEN inactivation may result in the transformation to melanoma in BRAF-mutated nevi, suggesting it may be important in the pathogenesis of NAM." (PMID 36834954, 2023). "Because PLK1 has already been shown to contribute to melanoma progression and poorer outcomes in general, we specifically focused on the relevance of PLK1 in BRAF-mutated melanoma and further investigated whether it may serve as a therapeutic target to overcome BRAFi resistance." (PMID 36768289, 2023).
melanoma (continued). "Melanoma is a multi-factorial disease, which depends on environmental characteristics, such as excess exposure to UV radiation from sun or artificial tanning procedures, genetic factors, such as phenotype of Fitzpatrick 1–3 skin type, BRAF activating mutations and tumor microenvironment." (PMID 36814240, 2023). "In addition, patients with BRAF V600-mutated melanoma, elevated LDH, and brain metastases have been shown to draw a higher magnitude of benefit in survival from combination ICI in comparison to anti-PD-1 monotherapy based on subgroup analyses of the CheckMate 067 study." (PMID 37887546, 2023). "Therefore, the clinical efficacy of ICIs may vary due to the distinct immune microenvironment in melanoma patients with different BRAF mutation status." (PMID 37205993, 2023). "Therefore, although further studies are needed, it is possible to hypothesize that inhibitors of PDH activity and/or of GSH biosynthesis could be used in combination with PLX4032 to overcome drug resistance of BRAF-mutated melanoma patients." (PMID 37534247, 2023). "Overall, these findings provide a new molecular method to classify melanoma patients carrying BRAF and NRAS mutations and help provide a broader view of the molecular characteristics of these patients that may help understand the signaling pathways and interactions involving the altered genes." (PMID 36982192, 2023). "Indeed, since nearly half of the human melanomas possess a V-RAF murine sarcoma viral oncogene homolog B (BRAF) mutation, BRAF and Mitogen-activated protein kinase kinase (MEK) inhibitors are used for targeted therapies, but with the relevant limitation of chemo-resistance." (PMID 37242600, 2023). "Furthermore, even though the evidence is still limited, BRAF non-V600-mutated melanomas may still benefit from BRAF/MEK inhibitors." (PMID 37958863, 2023). "Indeed, the best treatment for patients with BRAF-mutated melanoma is still debated." (PMID 36995534, 2023). "Importantly, given that the emergence and expansion of NCSCs have been shown to be independent of a tumour's initial driver mutations, these studies may also have implications for BRAF‐non‐mutant melanoma." (PMID 36967556, 2023). "Cdc42(G12V) has been implicated as a driver mutation in melanoma necessary for invasion of melanoma cells Furthermore, increased Cdc42 expression has been associated with a poorer prognosis and its effectors are associated with increased resistance to BRAF inhibitors." (PMID 37114375, 2023). "Melanoma development could be influenced by driver mutations such as BRAF, H/N/K-RAS, and C-KIT." (PMID 37483495, 2023). "Therefore, combined treatment with EZH2 and MEK1/2 inhibitors may provide a novel promising therapeutic strategy for NRAS-mutated and wild-type melanomas, as these types of melanomas are resistant to BRAF inhibitors." (PMID 37325482, 2023). "Furthermore, BRAF allele frequency has been shown to be of prognostic relevance in melanoma." (PMID 37796807, 2023). "In addition, LC-MS/MS proteomic analysis, supported by transcriptomic data mining, indicates for the first time that GALC may exert a pro-oncogenic impact on the proteomic landscape in BRAF-mutated human melanoma cells." (PMID 37445731, 2023). "In addition, though still disputable, several studies suggested BRAF status—a mutation occurring in approximately 50% of melanoma cases, could be a prognostic factor, as BRAF positive melanomas were typically more aggressive than those BRAF negative." (PMID 36161287, 2023). "Thus, it is likely that a glucocorticoid receptor antagonist (RU486) could increase the efficacy of BRAF-related therapy in BRAFV600E-mutated melanoma." (PMID 36766760, 2023). "Thus, possibly, a GR antagonist could increase the efficacy of BRAF-related therapy in BRAFV600E-mutated melanoma." (PMID 36766760, 2023).